RCN1 (reticulocalbin 1)
Diseases named in the same sentence as RCN1 in open-access papers (continued):
Sharing a sentence is not in itself a finding about the gene and the disease.
laryngeal carcinoma (3 papers, 2021 to 2024). Carcinoma that arises from the laryngeal epithelium. "Our results firstly demonstrated that RCN1 was a risk factor for laryngeal cancer." (PMID 34976784, 2021). "After RCN1 knockdown, migration and invasion of laryngeal cancer cells were investigated." (PMID 34976784, 2021). "RCN1 knockdown restrained migrated and invasive abilities of laryngeal cancer cells." (PMID 34976784, 2021). "Nevertheless, RCN1 expression is still undiscovered in laryngeal cancer." (PMID 34976784, 2021). "After silencing RCN1, invasion of laryngeal cancer cells was assessed through transwell assay." (PMID 34976784, 2021). "Among them, RCN1 (hazard ratio (HR): 1.928852, 95% confidence interval (CI): 1.194018-3.115926, p-value = 0.007261) and IBSP (HR: 1.928852, 95% CI: 1.194018-3.115926, p-value = 0.007261) were risk factors for laryngeal cancer." (PMID 34976784, 2021). "The data demonstrated that silencing RCN1 may restrain migration of laryngeal cancer cells." (PMID 34976784, 2021). "Our data confirmed that RCN1, DNAJA2, LASP1 and IBSP were up-regulated while LAT2, FUZ, HOOK2 and DAPK2 were down-regulated in laryngeal cancer." (PMID 34976784, 2021). "RCN1, DNAJA2, LASP1 and IBSP were up-regulated in laryngeal cancer." (PMID 34976784, 2021).
lymph node metastasis (3 papers, 2021 to 2024). "The results also showed that high expression of the RCN1 protein was significantly associated with lymph node metastasis in ESCC patients (p = 0.026) and advanced pathological stage (p = 0.045)." (PMID 38713738, 2024). "Moreover, our study found that high expression of RCN1 is associated with a poor prognosis in patients, rendering them more likely to develop lymph node metastasis." (PMID 38713738, 2024). "RCN1 expression correlates with lymph node metastasis, migration and invasion of cancer cells." (PMID 37723418, 2023).
clear cell renal cell carcinoma (2 papers, 2017 to 2025). "This study aims to investigate the RCN1 expression in clear cell renal cell carcinoma in correlation to different stages, tumor grades and overall patient survival and link the RCN1 expression to immune cell infiltration in ccRCC." (PMID 40975763, 2025). "In addition, RCN1 is transactivated by NF-κB and is positively correlated with poor survival in kidney clear cell carcinoma." (PMID 28319095, 2017). "In addition, on the basis of our bioinformatics analysis, RCN1 is correlated with poor survival in kidney clear cell carcinoma, thus suggesting that RCN1 may be a potential target for cancer therapy." (PMID 28319095, 2017). "Importantly, high RCN1 mRNA levels were correlated with poor survival rates in kidney clear cell carcinoma, thus suggesting that RCN1 may promote cancer progression." (PMID 28319095, 2017).
Down syndrome (2 papers, 2019 to 2023). "RCN1 encodes a protein involved in calcineurin regulation during calcium signalling and has similarity to human DSCR1 that is found in the Down Syndrome candidate region." (PMID 30665402, 2019).
invasive breast carcinoma (2 papers, 2015 to 2020). A carcinoma that infiltrates the breast parenchyma. "The gene expressions of ACOT7, STAT1, TYMP, and VOPP1 were significantly increased in invasive breast carcinoma, while the gene expressions of ACTG2, CNN1, CDC14B, NFIB, RCN1, and TRIM2 were dramatically downregulated in BRCA." (PMID 31986487, 2020).
keloid (2 papers, 2022 to 2025). An irregularly shaped, elevated mark on the skin caused by deposits of excessive amounts of collagen during wound healing. "Bioinformatics analysis showed that RCN1 carried out a number of functional activities, including calcium homeostasis and secretory cargo sorting and was upregulated in keloid." (PMID 40214031, 2025). "Our results suggested that RCN1 was upregulated, and knockdown of RCN1 alleviated keloid formation by inhibiting keloid fibroblasts proliferation, invasion, collagen production and promoting apoptosis." (PMID 40214031, 2025). "The results showed that overexpression of RCN1 dramatically increased the mRNA and protein levels of RCN1 in keloid fibroblasts." (PMID 40214031, 2025). "The mRNA and protein levels of RCN1 were significantly elevated in keloid tissues compared to those in normal skin tissues." (PMID 40214031, 2025). "The results of Western blotting indicated that the protein expression of ALKBH5, RCN1, IRE1α, and XBP1 were increased in skin tissues of keloid mice, and knockdown of RCN1 reversed the changes." (PMID 40214031, 2025). "And the protein levels of α‐SMA and COL1A1 were found to be upregulated in the skin tissues of keloid mice, and which were restored with the intervention of sh‐RCN1." (PMID 40214031, 2025). "In vivo experiments showed that knockdown of RCN1 significantly inhibited keloid formation by alleviating cell apoptosis and ER stress in mice." (PMID 40214031, 2025). "Taken together, these results confirmed that ALKBH5 played a vital role in the regulation of RCN1 in the proliferation, invasion, and apoptosis of keloid fibroblasts." (PMID 40214031, 2025). "Through detecting the protein expression of ALKBH5 and RCN1 in keloid fibroblasts, we confirmed that the transfection of pcDNA‐ALKBH5 and shRNA were successful." (PMID 40214031, 2025). "In this study, we demonstrated that ALKBH5 inhibits YTHDF2‐m6A‐mediated degradation of RCN1 mRNA to promote keloid formation by activating IRE1α‐XBP1‐mediated ER stress." (PMID 40214031, 2025). "In this study, we elucidated the role of RCN1 in the progression of keloid and its specific molecular mechanism by constructing keloid models in vivo and in vitro, aiming to identify potential targets for the treatment of keloid." (PMID 40214031, 2025). "To investigate the role of RCN1 in keloid tissues and keloid fibroblasts, we first detected RCN1 expression in normal skin and keloid tissues." (PMID 40214031, 2025). "Of these, CALU and RCN3 showed abnormally high expression levels with lower p values in keloids; while RCN1 was uniquely present in keloids." (PMID 35435317, 2022). "The aim of this study is to investigate the role of RCN1 in keloid." (PMID 40214031, 2025). "Reticulocalbin 1 (RCN1) was reported to be upregulated in keloid, but its molecular mechanism remains unclear." (PMID 40214031, 2025). "Herein, the keloid implantation model in the nude mice showed that knockdown of RCN1 could suppressed keloid formation in vivo." (PMID 40214031, 2025). "Our data revealed that RCN1 was upregulated by ALKBH5 to promote keloid formation by activating IRE1α‐XBP1‐mediated ER stress, RCN1 may be a potential biomarker for treatment of keloid." (PMID 40214031, 2025). "RCN1 was highly expressed in keloid tissues and keloid fibroblasts." (PMID 40214031, 2025). "In the current study, we probed a novel regulator RCN1 for keloid." (PMID 40214031, 2025). "In addition, the mRNA and protein expression of RCN1 was significantly upregulated in keloid fibroblasts compared to that in normal fibroblasts." (PMID 40214031, 2025). "Overall, the role of RCN1 described here may enable a deeper understanding of the keloid pathogenesis, thereby benefiting the clinical translation of keloids." (PMID 40214031, 2025). "Moreover, flow cytometry analysis indicated that overexpression of RCN1 significantly inhibited the apoptosis of keloid fibroblasts." (PMID 40214031, 2025).
keloid (continued). "Furthermore, overexpression of ALKBH5 inhibited cell apoptosis and promoted cell invasion, but this change was abolished with the intervention of knockdown of RCN1 in keloid fibroblasts." (PMID 40214031, 2025). "MTT assay revealed that overexpression of ALKBH5 significantly promoted the proliferation of keloid fibroblasts, which could be restored by silencing of RCN1." (PMID 40214031, 2025). "Finally, we established a mouse keloid model and injected mice with the RCN1 shRNA lentiviral vectors to monitor the keloid formation in mice." (PMID 40214031, 2025). "RCN1 was upregulated in keloid tissues and keloid fibroblasts compared to normal human skin." (PMID 40214031, 2025). "Thus, we speculated that the role of RCN1 in keloid fibroblasts may be related to ER stress." (PMID 40214031, 2025). "Overexpression of RCN1 activates ER stress by regulating IRE1α‐XBP1 pathway and promoting keloid formation." (PMID 40214031, 2025). "Thus, we inferred that RCN1 might play a crucial role in keloid formation." (PMID 40214031, 2025). "Moreover, overexpression of RCN1 significantly upregulated the protein levels of XBP1, GRP78, and IRE1α, and promoted ER stress in keloid fibroblasts, but this change was eliminated by sh‐XBP1 intervention." (PMID 40214031, 2025). "In our study, we found CALU, RCN3, and RCN1, the members of CREC protein family which carries out a number of functional activities, including calcium homeostasis and secretory cargo sorting, were significantly upregulated in keloids." (PMID 35435317, 2022). "We identified 206 proteins that showed significant differences in expression between keloid scars and normal skin tissues, including RCN3, RCN1, CALU, and PDGFRL which may play an import role in keloid formation." (PMID 35435317, 2022).
melanoma (2 papers, 2016 to 2021). A malignant, usually aggressive tumor composed of atypical, neoplastic melanocytes. "Recently, a novel protein, Reticulocalbin 1 (RCN1) which belongs to the CREC (Calumenin, Reticulocalbin 1 and 3, ERC-55, Cab-45) family was found to suppress ER stress-mediated apoptosis in murine melanoma and renal cancer cells." (PMID 33801941, 2021).
neuroblastoma (2 papers, 2019 to 2023). Neuroblastoma (NB) is the most common solid, extracranial childhood tumor. "Overall, we found that downregulation of 7 genes (Crb1, Lrrc9, Rcn1, Rtl1, Shisa3, Six6, St18) and upregulation of 2 genes (C1ql3, Slc18A1), are strongly predictive of favorable neuroblastoma outcome, consistent with delayed tumor development in Th-MYCN/Casp2−/− mice." (PMID 30670683, 2019).
Ssc (2 papers, 2021 to 2025). "Moreover, RCN1 was upregulated in dermal fibroblasts from patients with systemic sclerosis, therefore RCN1 can serve as a key regulator in fibroblasts." (PMID 40214031, 2025). "The regulatory function of calumenin in tissues that are affected by the processes of cytoskeleton rearrangement points out calumenin as a candidate prognostic biomarker in Ssc patients, like has been previously suggested for another member of the CREC family (reticulocalbin 1)." (PMID 34063287, 2021).
acute myeloid leukemia (1 paper, 2023). Acute myeloid leukemia (AML) is a group of neoplasms arising from precursor cells committed to the myeloid cell-line differentiation. "The mRNA levels of RCN1 in LAML (acute myeloid leukemia) patients were found to be approximately five times greater than those observed in normal bone marrow." (PMID 37746742, 2023). "Reticulocalbin‐1 (RCN1) is expressed aberrantly and at a high level in various tumors, including acute myeloid leukemia (AML), yet its impact on AML remains unclear." (PMID 37746742, 2023).
acute renal failure (1 paper, 2021). "All women with postpartum acute renal failure suffered from massive bleeding, which is characteristic of RCN1." (PMID 33479443, 2021).
atherosclerosis (1 paper, 2015). A disease characterized by the build-up of fatty material and calcium deposition in the arterial wall resulting in partial or complete occlusion of the arterial lumen. "Thus, Rcn1 on endothelial cell surface may facilitate phagocytosis of serological debris or deposits on the cell surface to prevent debris buildup and atherosclerosis." (PMID 25992960, 2015).
brain cancer (1 paper, 2021). A primary or metastatic malignant neoplasm affecting the brain. "Importantly, these findings will allow for the generation of drugs that block the function of EGFRvIII and RCN1 with the hope that these drugs will induce brain cancer cell death." (PMID 33801941, 2021).
esophageal squamous cell carcinoma (1 paper, 2024). Esophageal squamous cell carcinoma (ESCC) is a type of esophageal carcinoma (EC) that can affect any part of the esophagus, but is usually located in the upper or middle third. "Correlation analysis between RCN1 expression and clinicopathological characteristics in esophageal squamous cell carcinoma (ESCC) patients." (PMID 38713738, 2024). "The aim of this study was to explore the clinical value and biological role of RCN1 in esophageal squamous cell carcinoma (ESCC)." (PMID 38713738, 2024).
lymphoma (1 paper, 2025). A malignant (clonal) proliferation of B- lymphocytes or T- lymphocytes which involves the lymph nodes, bone marrow and/or extranodal sites. "When we correlated the RCN compositions in DLBCLs with the expression of HLA and B2M, we found that B2M and HLA-ABC–positive lymphomas consisted of a smaller proportion of the B cell rich with immune cells RCN1 (adj." (PMID 40772779, 2025).
medulloblastoma (1 paper, 2022). A malignant, invasive embryonal neoplasm arising from the cerebellum. "Two of the 5 selected linear fusions in cerebellum, namely SEPTIN7P14--PSPH and PAUPAR--RCN1, were also found in medulloblastoma." (PMID 35804907, 2022).
multiple sclerosis (1 paper, 2025). A progressive autoimmune disorder affecting the central nervous system resulting in demyelination. "GPX1, RCN1, and UBE2D3 exhibited AUC values above 0.7 in both datasets, indicating their potential as biomarkers for multiple sclerosis." (PMID 40650067, 2025).
oral cancer (1 paper, 2023). "The growth of malignant tumours is facilitated by the rapid proliferation of tumour cells, and in our study, we found that RCN1 could promote tumour cell proliferation, which makes RCN1 an important molecule in regulating the development of oral cancer." (PMID 38057406, 2023).
pituitary tumour (1 paper, 2024). "Transwell assays demonstrated that DLK1 and RCN1 promoted the invasion of pituitary tumour cells." (PMID 39548559, 2024).
renal tumor (1 paper, 2025). "Furthermore, we were able to observe that reticulocalbin-1 is homogenously expressed in tumors and that a knockdown of RCN1 can reduce the malign potential of renal tumor cells." (PMID 40975763, 2025).
skin cancer (1 paper, 2021). "Several reports indicating that RCN1 is responsible for promoting tumor survival in prostate, liver, kidney and skin cancer cell lines under ER stress." (PMID 33801941, 2021).
subependymoma (1 paper, 2010). Subependymoma is a rare and slow growing type of ependymoma, often presenting in middle-aged adults, found more commonly in men than in women, usually located in the fourth and lateral ventricles and manifesting with variable symptoms including headache, nausea, and loss of balance. "However, the detected deletion in the tumor cells did not affect this gene, again excluding a potential role for RCN1 in this subependymoma." (PMID 20500513, 2010).
cancer (24 papers, 2017 to 2025). A tumor composed of atypical neoplastic, often pleomorphic cells that invade other tissues. "Few is known about the role of RCN1 in cancer, yet downregulation of RCN1 has been implicated in the suppression of apoptosis after activation of the UPR47." (PMID 39890941, 2025). "HSPA5 and RCN1 are substantially elevated in cancer, and their levels associate with progression of malignancy." (PMID 37651191, 2023). "RCN1, a monomeric cell surface-associated protein encoding an endoplasmic reticulum (ER)-resident Ca2+-binding domain, plays a crucial role in cancer metastasis and development." (PMID 35436915, 2022). "The heatmap revealed that RCN1 was a risk factor in most cancers." (PMID 39828988, 2025). "Among these genes, RCN1, as an ER-resident calcium-binding protein, is verified as one of ER stress-related genes, of which the depletion causes the ER stress-induced cells’ apoptosis in various cancers." (PMID 34722631, 2021). "Additionally, as RCN1 is implicated in cancer biology beyond ccRCC, further investigation may offer novel therapeutic insight and accelerate drug development." (PMID 40975763, 2025). "Our study focuses on RCN1 and its role in ccRCC, deciphering also the mechanisms involved in cancer progression." (PMID 40975763, 2025). "This analysis highlights distinct expression patterns for ITIH2 and RCN1, suggesting their potential roles as biomarkers across various cancers." (PMID 40136513, 2025). "Further investigation into the core gene RCN1's prognostic ability in a pan‐cancer context was conducted using Cox modelling and Kaplan–Meier survival analysis." (PMID 39828988, 2025). "It acts together by inhibiting the expression of the RCN1 oncogene whose product suppresses the apoptosis of HCC cancer cells." (PMID 41465470, 2025). "To unravel the expression pattern of RCN1 in various cancers, we obtained pan-cancer expression data from the TIMER database." (PMID 38057406, 2023). "Dysregulation of RCN1 protein has been reported in multifarious diseases, including cancer, cardiovascular, and neuromuscular diseases." (PMID 34722631, 2021). "Reticulocalbin-1 (RCN1) is a calcium-binding protein, dysregulation of which contributes to tumorigenesis and progression in various cancers." (PMID 34722631, 2021). "Notably, RCN1 was identified as a critical oncogene that significantly influences cancer progression and serves as a promising therapeutic target." (PMID 39828988, 2025). "RCN1 was linked to cancer progression and its downregulation significantly suppresses PCa cell viability and arrests the cell cycles of DU145 and LNCaP cells, highlighting its potential as a therapeutic target in cancer treatment." (PMID 40136513, 2025). "Suppression of RCN1 facilitates apoptosis and necroptosis in cancer cells." (PMID 38475805, 2024). "In invasive cancer cells, RCN1 is overexpressed compared to poorly invasive cancer cells." (PMID 38475805, 2024). "Additionally, in nasopharyngeal carcinoma, knockdown of RCN1 has been shown to enhance drug sensitivity in cancer cells." (PMID 38057406, 2023). "Furthermore, we utilized the gene expression profiling interactive analysis 2 (GEPIA2) online tool to analyze RCN1 gene expression based on The Cancer Genome Atlas (TCGA) and Genotype‐Tissue Expression (GTEx) datasets." (PMID 37746742, 2023). "It has been suggested that RCN1 promotes cancer cell survival under hypoxia." (PMID 34663798, 2021). "Bioinformatics analysis of the TCGA database also revealed that, at the transcription level, RCN1 is positively correlated with NF-κB1 (RELA) and NF-κB2 in all collected cancer samples; these results indicate a positive correlation between RCN1 and NF-κB in cancer." (PMID 28319095, 2017). "RCN1 mainly functions in the endoplasmic reticulum; however, in ESCC, we found that RCN1 promotes cancer cell proliferation and growth by upregulating squamous epithelial cell development and inflammatory factors within the tumor microenvironment." (PMID 40244296, 2025).